ELF5 (E74 like ETS transcription factor 5)
Diseases named in the same sentence as ELF5 in open-access papers (continued):
Sharing a sentence is not in itself a finding about the gene and the disease.
COVID-19 (continued). "Here, we prioritise eight robust (e.g., ELF5) or suggestive but unreported (e.g., RAB2A) candidate protein mediators of COVID-19 outcomes by integrating results from the COVID-19 Host Genetics Initiative with population-based plasma proteomics using statistical colocalisation." (PMID 35970849, 2022). "The lead cis-pQTL for ELF5, rs766826 (MAF = 35.9%), has been reported by the COVID-19 HGI15 and is further in strong linkage disequilibrium (LD; r2 = 0.81) with a recently identified variant rs61882275 associated with severe COVID-19 in an independent study using whole genome sequencing." (PMID 35970849, 2022). "We finally observed potential signs of remodelling and high ELF5 expression in postmortem respiratory tissue samples of two COVID-19 patients with a fatal but not rapid disease course due to intensive treatment, including extracorporeal membrane oxygenation (≥14 days, termed as ‘later death’)." (PMID 35970849, 2022). "Other genes, such as ELF5 and FBRSL1 have no previously reported lung trait associations, and therefore, will need further mechanistic characterization to understand their role in severe COVID-19." (PMID 35360730, 2022).
prostate carcinoma (6 papers, 2015 to 2022). A carcinoma that arises from epithelial cells of the prostate gland. "In prostate cancer, loss of ELF5 protein expression correlates with loss of expression of the epithelial marker E-Cadherin and increased expression of the mesenchymal marker N-Cadherin." (PMID 30200227, 2018). "ELF5 was also found to physically interact with AR in prostate cancer cells and repress its transcriptional activity." (PMID 30200227, 2018). "ELF5 knockdown in prostate cancer cell lines induced EMT, particularly in the presence of TGFβ, and ELF5 was subsequently shown to block EMT by inhibiting TGFβ signaling through binding and suppressing SMAD3." (PMID 30200227, 2018). "To explore the function of ELF5 suppression in vivo, we analyzed xenografts of LNCaP prostate cancer cells." (PMID 28287091, 2017). "In prostate cancer, for example, ELF5 has been shown to inhibit transforming growth factor (TGF)-β-driven epithelial–mesenchymal transition by blocking phosphorylation of the TGF-β effector protein SMAD3." (PMID 26738740, 2016). "Conversely, ELF5 mRNA has been shown to be upregulated in a cell line model of prostate cancer progression involving acquisition of androgen independence." (PMID 26738740, 2016). "ELF5 is a member of the erythroblast transformation-specific (Ets) transcription factor family and is best known for its possible role in breast or prostate cancer, tissues with high fractions of epithelial cells, and less for its possible role in lung development and possibly cystic fibrosis." (PMID 35970849, 2022). "Furthermore, ELF5 expression is induced upon AR activation in prostate cancer cells and is a transcriptional target of AR, suggesting a role in negative feedback regulation of AR signaling." (PMID 30200227, 2018). "ELF5 expression was also significantly decreased in head and neck, lung, and prostate cancer." (PMID 26738740, 2016). "The transcription factor E74-like factor 5 (ELF5) is a potent antioncogene that can prevent epithelial-mesenchymal transition (EMT) and metastasis in prostate cancer (PCa)." (PMID 28287091, 2017). "In addition, the use of enzalutamide in clinically localized prostate cancer may potentiate metastasis independent of ELF5 expression." (PMID 28287091, 2017). "Elf5-induced MET was further confirmed in PC3 cells, a mesenchymal-like prostate cancer cell line with powerful invasiveness (data not shown)." (PMID 25629735, 2015).
bladder cancer (4 papers, 2015 to 2022). "A further mechanism of ESE transcription factor suppression in cancer is via promoter methylation, which has been reported for EHF in prostate and pancreatic cancer, and for ELF5 in bladder cancer." (PMID 30200227, 2018). "Downregulation of ELF5 in epithelial-like bladder cancer cell lines induced EMT, while its re-expression in mesenchymal-like T24 cells promoted MET." (PMID 30200227, 2018). "Subsequently, we analyzed methylation status of Elf5 promoter in bladder cancer samples (Cohort 2, n = 50), and found a methylation frequency of 72% (36/50)." (PMID 25629735, 2015). "Similarly, ELF5 mRNA and protein expression is decreased in urothelial (bladder) cancers compared to the normal urothelium, and is inversely correlated with bladder cancer grade." (PMID 30200227, 2018). "Increased ELF5 promoter methylation has also been demonstrated in bladder carcinoma." (PMID 26738740, 2016). "Overall, our clinical data support the supposed role that Elf5 may function to oppose bladder cancer progression." (PMID 25629735, 2015). "Together, our analyses conclude for the first time that the down-regulation of Elf5 by aberrant promoter methylation may promote bladder cancer recurrence in patients with primary NMIBC treated by TURBT." (PMID 25629735, 2015).
breast tumor (4 papers, 2015 to 2020). "To extend these findings clinically, we examined the relationship between hormone receptor status, anti-estrogen treatment and promoter methylation of DOK7 and ELF5 in a set of matched primary and recurrent breast tumors from 24 women." (PMID 26884724, 2016). "The negative correlation between ELF5 and SNAI2 expression seen in breast tumor clinical samples is similar to that observed in PPB specimens, suggesting that the decreased expression of ELF5 in PPB lung specimens can promote EMT." (PMID 33158935, 2020). "The relationship between hormone receptor status and promoter methylation of DOK7 and ELF5 was further examined using available methylation array data (Illumina HM450) from a set of paired primary and second breast tumors from 24 women." (PMID 26884724, 2016). "Among estrogen-regulated genes, progestin/PR-A counter-regulated a distinctive subset, including breast tumor progression genes (e.g., HES1, PRKCH, ELF5, TM4SF1), leading to invasiveness." (PMID 26356672, 2015). "This study characterizes the expression of hormone receptors, and the mRNA and DNA methylation levels of docking protein 7 (DOK7), and E74-like factor 5 (ELF5), in 21 novel tamoxifen-resistant cell lines and extends the findings to primary and recurrent human breast tumors." (PMID 26884724, 2016).
glioma (4 papers, 2018 to 2022). A benign or malignant brain and spinal cord tumor that arises from glial cells (astrocytes, oligodendrocytes, ependymal cells). "However, the molecular mechanisms of HOXC11, HOXC9, ELF5, and HNF4A function in the development and progression of gliomas remain unclear and require further exploration in the future." (PMID 33503296, 2021). "Amplification of ELF5 occur in cancers of the upper GI tract (oesophageal and stomach), ovary, head and neck, and breast in 2–6% of cases, while occasional deletions of ELF5 occur in prostate, sarcoma, bladder, and lung cancers as well as acute myeloid leukemia (AML) and gliomas." (PMID 30200227, 2018).
ovarian carcinoma (4 papers, 2014 to 2022). A malignant neoplasm originating from the surface ovarian epithelium. "Finally, ELF5 mRNA expression in ovarian cancer and ELF5 mRNA and protein in renal cell carcinoma is reduced compared to corresponding normal tissue, and re-expression of ELF5 in cell line models of these cancers inhibits cell proliferation and survival." (PMID 30200227, 2018). "We also chose two EHF-like family members (ELF-3 and ELF-5), which has been reported to be involved in ovarian cancer, to detect whether they can regulate LAIR promoter activity." (PMID 29915163, 2018). "Therefore, the WWOX gene may reverse the EMT in ovarian cancer stem cells by regulating the expression of the EMT regulatory factors, Elf5 and Snail." (PMID 24959289, 2014).
kidney cancer (3 papers, 2016 to 2021). Primary or metastatic malignant neoplasm involving the kidney. "Bladder and kidney carcinoma have been associated with loss of ELF5 expression at the protein and RNA levels, whereas in endometrial carcinoma ELF5 upregulation is associated with higher disease stage." (PMID 26738740, 2016). "The majority of evidence generated to date indicates ELF5 plays a tumour suppressive role in prostate, bladder, ovarian and renal cancer." (PMID 30200227, 2018). "Conversely, there was almost complete suppression of ELF5 expression in three kidney carcinoma subtypes." (PMID 26738740, 2016). "ELF5 has been characterized as a tumor suppressor in the kidney and bladder, and this may restrict kidney carcinomas to non-ELF5–expressing cells of origin." (PMID 26738740, 2016). "In particular, ELF5, SLC17A3, RALBP1, WNK1, APOC1, and CRYAB were experimentally verified to play an important role in the occurrence and development of kidney cancer." (PMID 34445498, 2021).
acute myeloid leukemia (2 papers, 2018 to 2023). Acute myeloid leukemia (AML) is a group of neoplasms arising from precursor cells committed to the myeloid cell-line differentiation. "In addition to EWSR1-FLI1 expression in Ewing sarcoma, the EWSR1 gene fuses to various genes in other cancers (e.g., EWSR1/ELF5 in acute myeloid leukemia, EWSR1/NR4A3 in extraskeletal myxoid chondrosarcomas, and EWSR1/CHOP in liposarcoma etc)." (PMID 36875767, 2023).
endometrial carcinoma (2 papers, 2016 to 2017). A malignant tumor arising from the epithelium that lines the cavity of the uterine body. "the upregulated ELF5 expression in endometrial carcinoma was also related to higher disease stage." (PMID 29209625, 2017).
head and neck cancer (2 papers, 2018 to 2023). A primary or metastatic malignant neoplasm affecting the head and neck. "ELF5 and IGSF10 mRNA levels are significantly decreased in human head and neck cancers." (PMID 36820942, 2023).
joint disease (2 papers, 2019 to 2021). "Changes in the methylation levels of genes associated with skin/joint disease (MBP, OSBPL5, SNORD115, and HCG26) and joint disease (IL22, ELF5, PPP2R2D, PTPRN2, and HCG26) were found." (PMID 33869291, 2021). "Biological inference prioritized notable DMRs associated with skin disease (SIGLEC14, JAM3, PCOLCE, RXRB), skin and/or joint disease (MBP, OSBPL5, SNORD115, HCG26), and joint disease (IL22, ELF5, PPP2R2D, PTPRN2, HCG26)." (PMID 30779748, 2019). "Although few DMRs exceeded a 10% change in methylation, it is noteworthy that many of those which did play roles in the pathogenesis of skin disease (SIGLEC14, JAM3, PCOLCE, RXRB, ELF5, IL22), joint disease (MBP, HCG26, IL22, PPP2R2D, PTPRN2) or are known to be imprinted (OSBPL5, SNORD115)." (PMID 30779748, 2019).
lung carcinoma (2 papers, 2016 to 2018). "In both lung carcinoma subtypes, there was a large variation in ELF5 levels, suggesting possible molecular subtype-specific expression patterns, similar to the breast." (PMID 26738740, 2016).
melanoma (2 papers, 2019 to 2020). A malignant, usually aggressive tumor composed of atypical, neoplastic melanocytes. "In particular, ELK3, ETS1, ETV1, ETV4, ETV5, and SPI1 were significantly upregulated in melanoma, whereas EHF, ELF3, ELF5, ERG, ETS2, ETV7, and SPDEF were significantly downregulated in the tumor." (PMID 33424867, 2020). "In addition, no studies have reported on the expression and function of ELK3, ETV5 ELF3, ELF5, ETS2, and SPDEF in melanoma." (PMID 33424867, 2020). "From the ETS family of TFs, ISMARA predicted GABPA, ELF2 and ELF5 with very low significance, while MIPRIP identified ETS1 as a highly significant regulator of TERT in the melanoma samples with a TERT promoter mutation." (PMID 31888467, 2019).
Obesity (2 papers, 2020 to 2024). Accumulation of substantial excess body fat. "It has also been reported that γδT cells secreted IL-17A, obesity induced GM-CSF and IL-5, periostin and Elf5 are associated with neutrophils recruitment in the lung." (PMID 33178575, 2020). "In patients with a BMI ≥30, SNP rs17713054 SLC6A20-LZTFL1 was associated with an elevation in Tsp (p = 0.02), while among patients without obesity (BMI <30) rs61882275 ELF5 (p = 0.003) was found to increase Tsp." (PMID 39175753, 2024).
alopecia (1 paper, 2022). Hair loss usually from the scalp. "Some members of this family, such as ETV2, have been found to promote hair growth through vascular regeneration in chemotherapy-induced alopecia, while Elf5, another ET family member, is expressed in the inner root sheath of hair follicles." (PMID 35625530, 2022).
Anosmia (1 paper, 2022). An inability to perceive odors. "Larger GWAS for anosmia and functional studies are needed to clarify a possible role of ELF5 in the onset of anosmia during SARS-CoV-2 infection." (PMID 35970849, 2022).
atherosclerosis (1 paper, 2022). A disease characterized by the build-up of fatty material and calcium deposition in the arterial wall resulting in partial or complete occlusion of the arterial lumen. "In an attempt to study the protective effect of Icariin on atherosclerosis, it was further demonstrated that enhanced expression of H19 by Icariin inhibited EndoMT in the endothelium upon ox-LDL treatment, possibly through miR-148b-3p and its target E74-like factor 5 (ELF5)." (PMID 35946958, 2022).
coronary artery disease (1 paper, 2016). "The three genome-wide significant results were then investigated further by examining their association with coronary artery disease (CAD) using a large sample (n = 5,765 CAD; n = 7,624 controls) with two linked SNPs, located in the ELF5 gene region, nominally significant." (PMID 27030319, 2016).
cystic fibrosis (1 paper, 2019). Autosomal recessive disorder caused by pathogenic variants in the CFTR gene (cystic fibrosis transmembrane conductance regulator), which encodes a chloride and bicarbonate channel expressed in epithelial cells, and follow the diagnosis criteria. "E74‐like factor 5 (ELF5) and ETS‐homologous factor (EHF) are epithelial selective ETS family transcription factors (TFs) encoded by genes at chr11p13, a region associated with cystic fibrosis lung disease severity." (PMID 31557407, 2019).
ductal carcinoma in situ (1 paper, 2017). "ELF5 represses EMT by suppressing SNAI2 expression and down regulating ESR1, and down regulation of ELF5 is detected in all stages of cancer progression including atypical ductal hyperplasia, ductal carcinoma in situ and invasive ductal carcinoma." (PMID 29016359, 2017).
Fibroadenoma (1 paper, 2016). A benign tumor of the breast characterized by the presence of stromal and epithelial elements. "In a separate study by Kuijper interrogating the transcriptome differences between five fibroadenomas and eight phyllodes tumors, CTAG1/2, PRAME, HOXC13, ELF5 and FABP7 were among 96 other transcripts found to be highly differentially expressed between fibroadenomas and phyllodes tumors." (PMID 26961242, 2016).
Hernia (1 paper, 2009). "The SNPs around the ELF5 region were in high linkage disequilibrium with each other, and a haplotype containing SNPs from ELF5 and CAT was highly significantly associated with hernia development." (PMID 19287495, 2009). "These genes may be involved in the estrogen receptor signaling pathway (KIF18A and NPTX1), the epithelial-mesenchymal transition (ELF5) and the collagen metabolism pathway (COL23A1), which are associated with the important molecular characteristics of hernia pathophysiology." (PMID 19287495, 2009).
lung disease (1 paper, 2019). "Our results are relevant to the involvement of both ELF5 and EHF in lung disease, since both genes are expressed in human bronchial epithelium." (PMID 31557407, 2019).
Miscarriage (1 paper, 2025). A pregnancy that ends at a stage in which the fetus is incapable of surviving on its own, defined as the spontaneous loss of a fetus before the 22th week of pregnancy. "The upregulation of genes such as Esrrb and Elf5 in PNA embryos indicates an increased risk of impaired trophoblast differentiation and miscarriage in the PCOS models examined in our study." (PMID 40385288, 2025).
teratoma (1 paper, 2016). A non-seminomatous germ cell tumor characterized by the presence of various tissues which correspond to the different germinal layers (endoderm, mesoderm, and ectoderm). "Furthermore, overexpression of Ssbp3 reduced the methylation level of the Elf5 promoter and promoted the generation of teratomas with internal hemorrhage, indicative of the presence of trophoblast cells." (PMID 27236334, 2016).
trophoblastic tumors (1 paper, 2024). "In summary, both our naïve and primed iPSC-derived TSC show trophoblast characteristics, including gene expression profiles similar to primary TSC, ELF5 promoter hypomethylation, and the ability to form in vivo trophoblastic tumors, consistent with previous reports." (PMID 38623329, 2024).